DNMT3A (DNA methyltransferase 3 alpha)
Diseases named in the same sentence as DNMT3A in open-access papers (continued):
Sharing a sentence is not in itself a finding about the gene and the disease.
acute myeloid leukemia (continued). "Mutations in epigenetic modifiers were reported in patients with acute myeloid leukaemia (AML) including mutations in DNA methyltransferase 3A gene (DNMT3A) in 20%-30% patients and mutations in isocitrate dehydrogenase 1/2 gene (IDH1/2) in 5%-15% patients." (PMID 24887327, 2014). "The role of DNMT3A in human cancer was highlighted by reports of DNMT3A mutations in approximately 20% of patients with acute myeloid leukemia." (PMID 24667323, 2014). "Mutations in DNA methyltransferase 3A (DNMT3A) gene were recently demonstrated in acute myeloid leukemia(AML)." (PMID 23305405, 2013). "DNMT3A and DNMT3B possess de novo methylation activity in mammalian cells, and mutations in DNMT3A occur in acute myeloid leukemia." (PMID 23857059, 2013). "The reprogramming of epigenetics in cancer has been recently supported by the finding of somatic mutations in DNMT3A in acute myeloid leukemia (AML)." (PMID 23162793, 2012). "Mutations in DNMT3A encoding DNA methyltransferase 3A were recently described in patients with acute myeloid leukemia." (PMID 22081665, 2011). "The hotspot DNMT3A mutations at the site of Arg822 (R882) promote polymerization, leading to aberrant DNA methylation that may contribute to the pathogenesis of acute myeloid leukemia (AML)." (PMID 38600075, 2024). "DNMT3A R882H and R882C are mutation hotspots in acute myeloid leukemia." (PMID 38600075, 2024). "Initially, somatic mutations in DNMT3A were identified in acute myeloid leukemia." (PMID 39902084, 2024). "DNMT3A is also frequently mutated in acute myeloid leukemia (AML) and T-cell lymphoma." (PMID 36810560, 2023). "Furthermore, increased transcription of CD44 mRNA was observed in human acute myeloid leukemia (AML) patients with FLT3 or DNMT3A mutations through the suppression of CpG islands methylation in the promoter." (PMID 37504249, 2023). "Furthermore, DNMT3A mutations in acute myeloid leukemia (AML) and T cell ALL are associated with poor prognosis of the patients." (PMID 36934225, 2023). "In addition, loss-of-function mutations in the DNMT3A gene are one of the most frequent defects identified in acute myeloid leukemia (AML; ~30%) or myelodysplastic syndrome (MDS; 2–10%) patients." (PMID 36979633, 2023). "Notably, DNMT3A−/− iHPCs recapitulate some DNA methylation patterns of acute myeloid leukemia (AML) with DNMT3A mutations." (PMID 35705990, 2022). "Numerous studies reveal DNMT3A mutation influences the acute myeloid leukemia progression." (PMID 35860691, 2022). "DNA methyltransferase 3A (DNMT3A) is responsible for the de novo methylation at C5 of cytosine (5mC) in CpG regions, and somatic mutations of DNMT3A have been implicated in >20% of cases of acute myeloid leukemia (AML)." (PMID 35048115, 2022). "DNMT3A encodes DNA methyltransferase, and is frequently mutated in acute myeloid leukemia." (PMID 34796114, 2021). "The DNA methyltransferase DNMT3A plays an important role in establishing the DNA methylation patterns during development and deregulation of DNMT3A is associated with hematological cancers, with the R882H mutation the most frequently occurring DNMT3A missense mutation in acute myeloid leukemia." (PMID 32385248, 2020). "However, sequencing of cancer genomes has identified mutations in DNMT3A in ~25% of patients with acute myeloid leukemia (AML), decreasing the catalytic activity of the enzyme." (PMID 30627525, 2018). "Xu Y, Sun Y, Shen H, Ding L, Yang Z, Qiu H, Sun A, Chen S, Wu D. Allogeneic hematopoietic stem cell transplantation could improve survival of cytogenetically normal adult acute myeloid leukemia patients with DNMT3A mutations." (PMID 30400835, 2018). "Furthermore, recurrent somatic DNMT3A mutations have been identified in acute myeloid leukemia and other hematological malignancies, indicating that impaired activity of DNMT3A is a causal factor of tumorigenesis." (PMID 27462454, 2016).
acute myeloid leukemia (continued). "Interestingly, common DNMT3A mutations have been recently described to arise early in the development of acute myeloid leukemia, a type of leukemia that preferentially occurs in the elderly." (PMID 27229519, 2016). "DNMT3A was the only predicted OG-like ERG with mutation hot spots in acute myeloid leukemia." (PMID 26110843, 2015). "By contrast, deletion of DNMT3A and DNMT3B in mouse hematopoietic stem cells impaired stem cell self renewal, the frequent DNMT3A mutations may be an parts of pathogenesis in acute myeloid leukemia." (PMID 23305405, 2013). "This study reveals causality‐enriched epigenetic clocks offer additional insight into acute myeloid leukemia (AML) specific DNA methylation remodeling, particularly when integrated with genetic stratification, like DNMT3A or IDH2 mutations." (PMID 41556261, 2026). "DNMT3A mutation (DNMT3AMut) is prevalent in adults, particularly in monocytic, and cytogenetically normal cases, affecting 25% of acute myeloid leukemia (AML) patients." (PMID 40151833, 2025). "Patients with acute myeloid leukemia (AML) harboring the DNA-methyltransferase 3 A (DNMT3A) R882 mutation (DR882MUT) usually have a high recurrence rate and poor prognosis." (PMID 40130394, 2025). "Although both types of mutations are predicted to reduce methyltransferase activity, DNMT3AR882 mutations appear to confer a significantly higher risk of progression to acute myeloid leukemia (AML) compared with non-R882 DNMT3A mutations." (PMID 38405837, 2024). "Although DNMT3A mutations in acute myeloid leukemia (AML) and myelodysplastic syndromes are almost exclusively heterozygous, patients with T-ALL can harbor homozygous or compound heterozygous DNMT3A mutations." (PMID 40552132, 2024). "Supporting these findings, DNMT3A mutations are frequently observed in adult patients with de novo Acute Myeloid Leukemia (AML), but they are rarely seen in pediatric AML." (PMID 39766049, 2024). "Somatic heterozygous mutations of DNMT3A, including a hotspot mutation affecting arginine 882 (R882) in the catalytic domain, are observed in acute myeloid leukemia (AML) and other hematologic malignancies." (PMID 37602556, 2023). "The patient was diagnosed with acute myeloid leukemia (AML)-M5b accompanied by DNMT3A, FLT3-TKD, and IDH2 mutations, chest CT revealed pulmonary tuberculosis (TB)." (PMID 37384044, 2023). "DNMT3A gene mutations, detected in 20-25% of de novo acute myeloid leukemia (AML) patients, are typically heterozygous." (PMID 37448520, 2023). "DNA-methyltransferase 3A (DNMT3A) mutations belong to the most frequent genetic aberrations found in adult acute myeloid leukemia (AML)." (PMID 35269477, 2022). "DNMT3A seems to be of particular relevance for hematopoietic differentiation, since it frequently reveals heterozygous mutations in acute myeloid leukemia (AML) and other hematological malignancies." (PMID 35705990, 2022). "DNMT3A mutations are also detected in ~20% of acute myeloid leukemia (AML) patients, and more than half of these mutations occur at the arginine 882 which is commonly mutated to histidine (R882H) or cysteine (R882C)." (PMID 34663800, 2021). "Somatic mutations in the DNMT3A gene are also the most common cause of clonal hematopoiesis, and can initiate acute myeloid leukemia (AML)." (PMID 34315901, 2021). "Somatic mutations in DNMT3A have been identified in approximately 25% of patients with acute myeloid leukemia (AML), with Arg882 (R882) being the hotspot." (PMID 34067359, 2021). "Mutations in TET2 and DNMT3A are also frequently associated with myeloid malignancies, including acute myeloid leukemia (AML), myeloproliferative neoplasms (MPN), and myelodysplastic/myeloproliferative neoplasms (MDS/MPN)." (PMID 34581268, 2021). "DNA (cytosine-5)-methyltransferase 3A (DNMT3A)-mutated acute myeloid leukemia (AML) has a poor prognosis, but the exact mechanism is still unclear." (PMID 34093541, 2021).
acute myeloid leukemia (continued). "DNMT3A-affecting mutations, known to drive acute myeloid leukemias (AML), were observed in three adult patients in the in-house cohort and none of the pediatric T-ALLs." (PMID 33225950, 2020). "Among these, mutation of DNMT3A has been identified in ~25% acute myeloid leukemia (AML) patients, which gives rise to aberrant DNA methylation patterns and increased cell proliferation, and correlates with poor clinical outcome." (PMID 32385248, 2020). "DNA methyltransferase 3 alpha (DNMT3A) mutation was one of the most frequent genetic alterations in acute myeloid leukemia (AML), which was associated with poor prognosis and appeared to be a potential biomarker." (PMID 33299888, 2020). "The R882H DNMT3A is a hotspot mutation in acute myeloid leukemia (AML) causing aberrant DNA methylation." (PMID 32385248, 2020). "Up to 22% of acute myeloid leukemia (AML) patients carry a somatic variant in DNMT3A and these alterations have been associated with poor prognosis and adverse survival outcomes for AML patients." (PMID 33182397, 2020). "The influence of DNMT3A R882 mutations on adult acute myeloid leukemia (AML) prognosis is still controversial presently." (PMID 31291961, 2019). "Human de novo MTase DNMT3A is most frequently mutated in acute myeloid leukemia (AML) with a striking prevalence of R882H mutation, which has been extensively studied." (PMID 31861499, 2019). "We have previously demonstrated that acute myeloid leukemia (AML) patients frequently display aberrant hypermethylation in DNMT3A, which is rather mutually exclusive with genomic mutations in this gene." (PMID 31552094, 2019). "More recently, a high prevalence of DNMT3A somatic mutations were observed in hematological malignancies, Acute Myeloid Leukemia (AML) and Myelodysplastic syndrome (MDS)." (PMID 31091831, 2019). "Notably, in acute myeloid leukemia expression of transcript 2 correlates with its in vitro DNA methylation and gene expression signatures and is associated with overall survival, indicating that DNMT3A variants also affect malignancies." (PMID 30582132, 2018). "Acute myeloid leukemia (AML) is frequently associated with genomic mutations in DNMT3A—either at the highly recurrent position R882 or at other sites within this gene." (PMID 30582132, 2018). "DNMT3A mutations are frequently discovered in acute myeloid leukemia (AML), associated with poor outcome." (PMID 27724883, 2016). "In acute myeloid leukemia (AML), the DNMT3A enzyme is frequently mutated with approximately 20% of patients having some form of coding mutation." (PMID 26483790, 2015). "DNMT3A mutations represent one of the most frequent gene alterations detectable in acute myeloid leukemia (AML) with normal karyotype." (PMID 25994761, 2015). "DNMT3A mutations and deletions have been previously observed in acute myeloid leukemia (AML), myelodysplastic sydromes and myeloproliferative neoplasms." (PMID 23946816, 2013). "Somatic mutations of DNMT3A gene have recently been reported in acute myeloid leukemia (AML) and myelodysplastic syndrome (MDS)." (PMID 22066015, 2011). "Hydralazine has also been reported to suppress DNMT3a expression, and DNMT3A mutations are implicated in the development of various hematologic neoplasms, including myeloproliferative neoplasms, MDS, acute myeloid leukemia (AML), and T-cell lymphoma." (PMID 41343491, 2025). "DNA methyltransferases, such as DNMT1, DNMT3A, and DNMT3B, have been implicated in the progression of multiple malignancies including breast cancer and acute myeloid leukemia." (PMID 40427627, 2025). "DNA methyltransferase 3A (DNMT3A) and isocitrate dehydrogenase 1 and 2 (IDH1/2) are genes involved in epigenetic regulation, each mutated in 7–23% of patients with acute myeloid leukemia." (PMID 38791049, 2024). "The patient was diagnosed with acute myeloid leukemia (FLT3, DNMT3A, U2AF1, and SMC3 mutations; KMT2A amplification; high-risk) and adenocarcinoma of the cardia." (PMID 39121277, 2024).
acute myeloid leukemia (continued). "In the present case, the final diagnosis was acute myeloid leukemia (FLT3, DNMT3A, U2AF1, and SMC3 mutations; KMT2A amplification; high-risk) with adenocarcinoma of the cardia." (PMID 39121277, 2024). "Here, we characterize the DNA methylation phenotypes of bone marrow cells from mice with hematopoietic deficiency of Dnmt3a or Dnmt3b (or both enzymes) or expressing the dominant-negative Dnmt3aR878H mutation [R882H in humans; the most common DNMT3A mutation found in acute myeloid leukemia (AML)]." (PMID 38295174, 2024). "Several research teams have determined that mutants of the DNMT3A enzyme are often present in patients with acute myeloid leukemia." (PMID 39334883, 2024). "Similarly, DNMT3A mutations associated with acute myeloid leukemia (AML) can be found at either the RD or FF interface." (PMID 38429855, 2024). "DNMT3A was also overexpressed in many human cancers such as pituitary adenoma, acute myeloid leukemia, and vulvar squamous cell carcinoma and led to the silencing of tumor suppressors such as p16 and RASSF1A." (PMID 36979633, 2023). "Treatment with the hypomethylating agents’ showed efficacy in myelodysplastic syndrome and acute myeloid leukemia, a response that appears to correlate with IDH1/2, TET2, and DNMT3A mutations." (PMID 37998740, 2023). "In addition, DNMT3A is found to be mutated at a high rate in acute myeloid leukemia (AML) and associated with poor prognosis." (PMID 36091786, 2022). "Mutations in DNMT3A are observed in approximately 22% of acute myeloid leukemia (AML)." (PMID 36329185, 2022). "In contrast, clones with ASXL1 and DNMT3A mutations are inclined to grow over time and are associated with a lack of response to immunosuppressive therapy, and with the evolution towards MDS/Acute Myeloid Leukemia (AML)." (PMID 36233062, 2022). "Internal tandem duplications (ITD) of the FMS-like tyrosine kinase 3 (FLT3) predict poor prognosis in acute myeloid leukemia (AML) and often co-exist with inactivating DNMT3A mutations." (PMID 34903841, 2022). "AGT was negatively related to DNMT3A/DNMT3B in acute myeloid leukemia (LAML) and to DNMT1/DNMT3B in LGG." (PMID 34671200, 2021). "Mutated TET2 can promote and inhibit HSC differentiation, and loss of DNMT3A function could lead to transformation in acute myeloid leukemia (AML)." (PMID 34684081, 2021). "MPNs are stem cell diseases: clonal evolution in acute myeloid leukemia occurs if additional mutations appear, such as ASXL1, TET2, DNMT3A, SF3B1, or SFSR2." (PMID 34684081, 2021). "Recurrent TET2, DNMT3A, IDH1/2 mutations have been observed in patients with myeloproliferative neoplasms and other hematological malignancies, such as acute myeloid leukemia (AML), chronic myelomonocytic leukemia (CMML), or myelodysplastic syndromes (MDS)." (PMID 33803981, 2021). "DNMT1 and DNMT3b are found to plays roles in the development of central nervous system, while DNMT3a has important functions in acute myeloid leukemia." (PMID 32408199, 2020). "DNMT1 alterations have been described in colorectal cancer, whereas DNMT3A mutations have been often reported in myelodysplastic syndromes (MDS) and are associated with poor survival in acute myeloid leukemia (AML)." (PMID 33339101, 2020). "Soon after, it was validated that miR-29b induces DNA hypomethylation universally in acute myeloid leukaemia (AML) by direct downregulation of DNMT3a and DNMT3b and indirect repression of DNMT1." (PMID 33050637, 2020). "DNMT3A mutations are also frequent in acute myeloid leukemia (AML) patients." (PMID 30813436, 2019). "Somatic mutations of DNMT3A occur in about 20% of acute myeloid leukemia (AML) patients." (PMID 31827512, 2019). "Mutations in DNA methyltransferase DNMT3A were identified in 25% of acute myeloid leukemia (AML)." (PMID 31497535, 2019). "For example, DNMT3A is commonly mutated in acute myeloid leukemia (AML) and T cell lymphomas." (PMID 31097014, 2019).
acute myeloid leukemia (continued). "Previously, EPZ00477 showed a good effect on the treatment of mixed lineage leukemia and DNMT3A-mutant acute myeloid leukemia." (PMID 31888761, 2019). "In the acute myeloid leukemia (LAML) cohort, 1.38% of missense mutations were in DNMT3A gene (p.R882H), 1.05% were IDH2 p.R140Q, and 0.79% were IDH1 p.R132C." (PMID 30890735, 2019). "DNMT3A is recurrently mutated in acute myeloid leukemia (AML) and other myeloid malignancies." (PMID 31695915, 2019). "This study aimed to evaluate DNMT3A exon 23 mutations and their prognostic impacts in the presence of NPM1 and FLT3 mutations in acute myeloid leukemia (AML) patients who underwent allogeneic hematopoietic stem cell transplantation (HSCT)." (PMID 29786546, 2018). "Mutation of DNMT3A gene has been reported in patients with myeloid malignancies, including myelodysplastic syndromes (MDS) and acute myeloid leukemia (AML)." (PMID 29619119, 2018). "In humans, around 20% of AML (acute myeloid leukemia) and MDS (myelodysplastic syndromes) patients carrying mutations in DNMT3A suffer from the loss of over 50% of DNA methylation." (PMID 29710796, 2018). "Critical findings on DNMT3A variation have suggested that DNMT3A is frequently mutated in acute myeloid leukemia (AML), myelodysplastic syndrome (MDS) and adult early T-cell precursor acute lymphoblastic leukemia (ETP-ALL) and is associated with disease aggressiveness and treatment resistance." (PMID 28127428, 2017). "Mutations in known tumor suppressors DNMT3A (p.G728D) and ASXL1 (p.E657fs), consistent with mutations of known consequence in acute myeloid leukemia, were identified." (PMID 25000259, 2014). "For example, DNMT3A mutant pre-LSCs were shown to survive chemotherapy and represent a reservoir for leukemic progression and hematological relapse in acute myeloid leukemia (AML)." (PMID 25522333, 2014). "De novo acute myeloid leukemia (AML) with concurrent DNMT3A, FLT3 and NPM1 mutations (AMLDNMT3A/FLT3/NPM1) has been suggested to represent a unique AML subset on the basis of integrative genomic analysis, but the clinical features of such patients have not been characterized systematically." (PMID 25281355, 2014). "Steensma points out in this regard that “the presence of DNMT3A, NPM1, or MLL mutations influences dose response to daunorubicin, which is used to treat AML (Acute Myelogenous Leukemia)”." (PMID 25562649, 2013). "Recently, BCOR has been described as mutated in a subset of acute myeloid leukemia patients; about 50% of which present with both BCOR and DNMT3A mutations suggesting a potential cooperation of the two genes, possibly through an epigenetic mechanisms." (PMID 23577124, 2013). "Somatic DNMT3A mutations have been described in approximately 20% of acute myeloid leukemia (AML) patients, especially in those with an intermediate risk cytogenetic profile and although they did not affect the 5-methylcytosine content they were associated with poor clinical outcome." (PMID 23533770, 2013). "Common in both acute myeloid leukemia (AML) and myelodysplastic syndromes, TET2 mutations drive hypermethylation patterns similar to those produced by DNMT3A loss-of-function mutations using DNA demethylation by conversion of 5-methylcytosine to 5-hydroxymethylcytosine." (PMID 40581650, 2025). "The main factor associated with T-ALL hypermethylation appears to be the tumor type, as mice that develop acute myeloid leukemia (LAML) do not show substantial patient-like CGI methylation even when using the same genetic drivers (e.g. loss of DNMT3A)." (PMID 40676699, 2025). "DNMT3A and TET2 are also candidate genes for CHIP mutations, as loss-of-function mutations in these genes are commonly detected in the peripheral blood samples of patients with myelodysplastic syndromes and acute myeloid leukemia." (PMID 40365343, 2025).